RNU6-43P (RNA, U6 small nuclear 43, pseudogene)
Synonyms: RNU6-43
Gene: Small nuclear RNA gene on chromosome 10 (102,591,524 to 102,591,630, forward strand). Ensembl gene ENSG00000207029.
Homologues: Orthologues: chimpanzee U6 (98% identical). Paralogues in human: RNU6-11P (94% identical), RNU6-37P (94% identical), RNU6-24P (93% identical), RNU6-25P (93% identical), RNU6-33P (93% identical), RNU6-727P (93% identical), RNU6-1 (93% identical), RNU6-1216P (93% identical), RNU6-15P (93% identical), RNU6-19P (93% identical), RNU6-2 (93% identical), RNU6-23P (93% identical), and 1285 more.